KCNJ11 (potassium inwardly rectifying channel subfamily J member 11)
Diseases named in the same sentence as KCNJ11 in open-access papers (continued):
Sharing a sentence is not in itself a finding about the gene and the disease.
diabetes (continued). "We analysed the most relevant common neonatal diabetes genes (KCNJ11, ABCC8, INS) to exclude monogenic diabetes in infancy-onset diabetes (n = 8 patients with manifestation before age 12 months)." (PMID 28534863, 2017). "The KCNJ11 gene is related to permanent neonatal diabetes mellitus (PNDM), a rare form of diabetes starting before the age of 6 months." (PMID 19794883, 2009). "Of interest, a patient with KCNJ11-TNDM with diabetes onset in 2022 entered remission without any insulin or sulfonylurea treatment, confirming an observation we made in 2 other patients with TNDM associated with KCNJ11 pathogenic variants." (PMID 38408297, 2024). "ABCC8, KCNJ11 and INS are the most commonly involved genes in this age group and maybe present on a generic monogenic diabetes panel." (PMID 37033247, 2023). "No cases of monogenic diabetes were found in the small subpopulations tested with diabetes diagnosed 12-24 months in three studies sequencing KCNJ11 and INS genes only (n = 58–70)." (PMID 37794142, 2023). "Kir6.2 (KCNJ11), SUR1, and SUR2 are overexpressed in the cell lines and biopsies of patients with CC; in addition, when treating the cell lines with glibenclamide (a drug used in the treatment of diabetes that blocks KCNJ11), cell proliferation was inhibited." (PMID 37408210, 2023). "Both KCNJ11 and ABCC8 genes are useful in diagnosing monogenic diabetes during infancy." (PMID 34584998, 2021). "No other clear clinical manifestation besides diabetes has been described for patients with heterozygous mutations in KLF11 (MODY7), ABCC8 (MODY12), KCNJ11 (MODY13), and APPL1 (MODY14)." (PMID 34079523, 2021). "In 33 (13%) patients, class 4–5 variants were identified in one of four genes usually considered as rarely involved in monogenic diabetes in adults, namely HNF1B (15 cases, 6.0%, among which 10 HNF1B whole-gene deletion), ABCC8 (8 cases, 3.2%), KCNJ11 (3 cases, 1.2%), and INS (7 cases, 2.8%)." (PMID 31291970, 2019). "A previous study has evaluated the significance of certain genetic variants on diabetes risk in the entire ARIC cohort; however, this study did not include the rs5219 KCNJ11 variant." (PMID 30169531, 2018). "Additionally, in this combined cohort, we found that genetic variants of the KCNJ11 gene are not significant predictors of diabetes risk for either race; and, these genetic variants are not effect modifiers of the association between serum K and incident diabetes for either race." (PMID 30169531, 2018). "However, they are related to diabetes or insulin secretion (rs757110 in ABCC8, rs5215 and rs5219 in KCNJ11), carotid intima media thickness (rs2468844 in SAA2), and oligospermia (rs11703684 in PIWIL3)." (PMID 27900359, 2016). "The associations of 23 SNPs located within 17 candidate genes (MTHFR, PPARγ, LPL, INSIG, TCF7L2, FTO, KCNJ11, JAZF1, CDKN2A/B, ADIPOQ, WFS1, CDKAL1, IGF2BP2, KCNQ1, MTNR1B, IRS1, ACE) with overweight and obesity, diabetes, metabolic phenotypes, and MetS were examined in both studies." (PMID 24959828, 2014). "Furthermore the study aimed at determining whether mutations in KCNJ11, ABCC8, HNF1A, HNF4A or INS are common in AAB negative diabetes." (PMID 20863361, 2010). "Indeed, without the gene discovery and the clinical trial of targeted therapy in humans, people with KCNJ11 PNDM would have remained on a treatment that was not very efficient and that allowed only suboptimal glycaemic control, leading to increased risk of long-term diabetes complications." (PMID 30599002, 2018). "Thus the search for a genetic defect in KATP (KCNJ11, ABCC8) or INS genes was justified, but the severe, non syndromic diabetes initially observed in our proband was not compatible with a loss-of-function GCK variant." (PMID 40244428, 2025).
type 2 diabetes (83 papers, 2003 to 2025). "One of these variants, ADCY3 c.3380C>G, is involved in the development of obesity, while the other, KCNJ11 c.628A>G, is associated with type 2 diabetes and neonatal diabetes." (PMID 40149731, 2025). "Despite the reported association of KCNJ11 polymorphisms with increased risk of type 2 diabetes and pharmacogenetic responses to antidiabetic medications, their role in the regulation of kidney function appears to be minor." (PMID 40870982, 2025). "To conclude, the current study can be considered the most comprehensive association meta-analysis of KCNJ11 polymorphisms with type 2 diabetes incidence, which can expand our knowledge about the role of this gene in T2D incidence." (PMID 36456687, 2022). "In parallels with neonatal diabetes, alteration in Katp channel function also plays an etiological role in the development of type 2 diabetes with the E23K/S1119 KCNJ11/ABCC8 variants associated with a 1.32 increase in the risk of type 2 diabetes." (PMID 33693776, 2021). "Two individual polymorphisms (ADIPOQ rs1501299, KCNJ11 rs5219) were found to be associated with type 2 diabetes." (PMID 30467975, 2019). "With the exception of the genetic variant in KCNJ11, all type 2 diabetes susceptibility variants had higher allele frequencies in subjects with type 2 diabetes than in controls." (PMID 28649285, 2017). "Another study on arab population showed significant association of the KCNJ11 E23K polymorphism with type 2 diabetes." (PMID 28330327, 2016). "A common polymorphism (E23K) in KCNJ11 is associated with increased susceptibility to type 2 diabetes." (PMID 27118464, 2016). "A study also characterized novel mutations in ABCC8 and KCNJ11 in the Russian population, which were novel loci for susceptibility to both type II diabetes and altered insulin secretion." (PMID 25871929, 2015). "In conclusion, the E23K variant of the KCNJ11 gene conferred higher susceptibility to type 2 diabetes in children/adolescents." (PMID 25309595, 2014). "Two further classic type 2 diabetes risk alleles, KCNJ11 rs5219 (G) (influencing insulin secretion) and PPARγ rs1801282 (C) (influencing insulin sensitivity) are considered to be very rare and very frequent, respectively, in individuals of African descent." (PMID 24059590, 2013). "A number of activating mutations and an E23K polymorphism of Kcnj11 are related to the development of insulin resistance and type-2 diabetes." (PMID 20307313, 2010). "More recently, evidence has accumulated supporting a role for the E23K variant of KCNJ11 (LocusLink ID 3767) in Type 2 diabetes predisposition." (PMID 14551916, 2003). "However, type 2 diabetes has a complicated genetic architecture that numerous genetic variants shape it, while we considered only essential variants of the KCNJ11 gene in the current study." (PMID 36456687, 2022). "Two variants in KCNJ11, rs5215 and rs5219, are associated with an increased risk of type 2 diabetes in Caucasians and East Asians; and rs5215 has also been found to be a significant predictor of type 2 diabetes in African Americans." (PMID 30169531, 2018). "Additionally, there was a strong upregulation of several K+ channel genes in Aldh1b1tm1lacZ null islets, including Kcnj11, a type 2 diabetes risk factor, and expression of adenylate cyclases Adcy4 and Adcy5 was repressed." (PMID 26518685, 2016). "As for KCNJ11 rs5219, only few studies have examined the importance of the G allele in blacks: In an African American population, it was associated with reduced odds of type 2 diabetes; the frequency was 0.06." (PMID 24059590, 2013). "For example, the GWAS SNP rs5215 in KCNJ11 is known to be associated with Type II diabetes." (PMID 22551073, 2012). "Despite the importance of KCNJ11 polymorphisms, the lack of a comprehensive genetic association study among Iranians, a population with an unknown genetic makeup, motivated us to discover the possible involvement of the KCNJ11 polymorphisms in type 2 diabetes development across Iranians." (PMID 36456687, 2022).
type 2 diabetes (continued). "Due to the central role in insulin secretion, the potassium inwardly-rectifying channel subfamily J member 11 (KCNJ11) gene is one of the essential genes for type 2 diabetes (T2D) predisposition." (PMID 36456687, 2022). "KCNJ11 has attracted considerable interest in recent years as candidate gene for Type 2 diabetes (T2D) and has a reported 180 single nucleotide polymorphisms (SNPs) in NCBI (National Centre for Biotechnology Information) database for humans." (PMID 25247988, 2014). "DNA methylation and other epigenetic modifications influence the insulin secretion and potassium channel regulation functions of the type 2 diabetes gene potassium voltage-gated channel subfamily J member 11 (KCNJ11), which is located on chromosome 11p15.1." (PMID 40225541, 2025). "Mutations in the KCNJ11 gene that encodes the Kir6.2 protein (a major constituent of KATP channels) were reported to be associated with Type 2 DM, neonatal diabetes mellitus (NDM), and maturity-onset diabetes of the young (MODY)." (PMID 38675722, 2024). "The majority of KCNJ11 gene mutations causing MODY 13 were from G to A. The incidence rates of chronic complications were lower than type 1 and type 2 diabetes." (PMID 38095268, 2024). "The preserved incretin response in adults with KCNJ11‐PNDM contrasts with the reduced post‐meal GLP‐1 that is often seen in adults with type 2 diabetes." (PMID 37602910, 2023). "Here, we examined the association of common variants of KCNJ11 with type 2 diabetes incidence in the Iranian cohort, followed by carrying out the most comprehensive meta-analysis to assess the potential role of KCNJ11 polymorphisms in T2D susceptibility." (PMID 36456687, 2022). "The ABCC8 promoter is linked to a distal intergenic GWAS SNP rs1557765 (body mass index) as well as three KCNJ11 intronic GWAS SNPs rs5215, rs5219, and rs757110 (type 2 diabetes) by pcHi-C data." (PMID 34425882, 2021). "Among these effector genes are ABCC8, KCNJ11, PDX1, ADCY5, and KCNQ1, which are recognized as pancreatic β-cell genes strongly associated with type 2 diabetes." (PMID 34425882, 2021). "Genetic polymorphisms in CDKAL1, CDKN2A/2B, KCNJ11, KCNQ1, and PEPD that we selected as potential effect modifiers were found to be associated with type 2 diabetes in the East Asian population." (PMID 32722593, 2020). "(iii) KCNJ11 (rs5210) and KCNQ1 (rs2237895) gene variants are significantly associated with type 2 diabetes in the Indian population." (PMID 33101408, 2020). "For example, several GWAS loci for type 2 diabetes contain genes known to harbour causal coding variants for rare Mendelian syndromes related to type 2 diabetes (e.g. HNF1A, HNF1B, WFS1, PPARG, KCNJ11, HNF4A, GCK)." (PMID 26702037, 2015). "Other examples of successful drugs targeting genes that arise (with small effect sizes) in GWAS include PCSK9 for LDL cholesterol, and PPARG and KCNJ11 for type 2 diabetes." (PMID 26702037, 2015). "Evidence accumulated so far suggests that the E23K polymorphism of the KCNJ11 gene, which encodes the Kir6.2 subunit of the KATP channel, is a candidate gene for type 2 diabetes reported mostly from adults." (PMID 25309595, 2014). "The GMDR has been successful in identifying the significant interaction of CHRNA4 with CHRNB2, NTRK2 with BDNF, and GABBR1 with GABBR2 in nicotine dependence, of LEPR and ADRB2 in obesity, and of HNF4A and KCNJ11 in type 2 diabetes (T2D)." (PMID 23626757, 2013). "TCF7L2 rs7903146, KCNJ11 rs5219, PPARγ rs1801282 and CAPN10 rs3842570, rs3792267, and rs5030952 were typed and associations with type 2 diabetes and phenotypic traits examined." (PMID 24059590, 2013). "Surprisingly, we are the first to investigate the importance of PPARγ rs1801282 and KCNJ11 rs5219 for type 2 diabetes in West Africa." (PMID 24059590, 2013). "In conclusion, we confirmed the association between PPARG, KCNJ11, CDKAL1, CDKN2A-CDKN2B, IDE-KIF11-HHEX, IGF2BP2, SLC30A8 variants and type 2 diabetes." (PMID 19862325, 2009).
type 2 diabetes (continued). "We confirmed the effects of SNPs from PPARG, KCNJ11, CDKAL1, CDKN2A-CDKN2B, IDE-KIF11-HHEX, IGF2BP2 and SLC30A8 on risk for type 2 diabetes, with odds ratios ranging from 1.114 to 1.406 (P value range from 0.0335 to 1.37E-12)." (PMID 19862325, 2009). "The current study confirmed the association between PPARG, KCNJ11, CDKAL1, CDKN2A-CDKN2B, IDE-KIF11-HHEX, IGF2BP2 and SLC30A8 and type 2 diabetes." (PMID 19862325, 2009). "We report a novel loss-of-function mutation in KCNJ11 (encoding Kir6.2) that results in a clinical phenotype largely indistinguishable from common gestational and type 2 diabetes, and was only identified by genetic screening." (PMID 38366195, 2024). "We did not observe significant interactions by five single nucleotide polymorphisms (SNPs) related to type 2 diabetes (CDKAL1 rs7756992, CDKN2A/B rs10811661, KCNJ11 rs5215, KCNQ1 rs163184, and PEPD rs3786897) in the association between coffee and the risk of type 2 diabetes." (PMID 32722593, 2020). "In type II diabetes mellitus, insulin secretion, integration of energy metabolism pathways, KCNJ11, and ABCC8 were the common targets, which may be regulated by XSN." (PMID 31607935, 2019). "The protective allele of PPARγ rs1801282 and the risk-conferring allele of KCNJ11 rs5219 are nearly absent and thus have a debatable relevance for population-wide variation in type 2 diabetes risk in this area." (PMID 24059590, 2013). "Thus, common variants in KCNJ11 and ABCC8 were logical selection also for pharmacogenetic studies in type 2 diabetes." (PMID 24324494, 2013). "The results demonstrated that genetic variation in KCNJ11, BDNF, PFKP, PTER and SEC16B were associated with SGA and support the concept that genetic factors associated with obesity and/or type 2 diabetes are more prevalent in those born SGA compared to those born AGA." (PMID 20712903, 2010). "In addition, SNPs from PPARG, KCNJ11, CDKAL1, IDE-KIF11-HHEX, IGF2BP2 and SLC30A8 were also moderately associated with type 2 diabetes, with ORs ranging from 1.114 to 1.282 (P<0.05)." (PMID 19862325, 2009). "Gain-of-function mutations and common variants in the human genes encoding the pore-forming (KCNJ11) and regulatory (ABCC8) subunits of the KATP channel have been implicated in neonatal diabetes (ND), early-onset diabetes, and an increased risk of developing type 2 diabetes later in life." (PMID 41189737, 2025). "Similarly, variants of the KCNJ11 and HNF4A genes could cause MODY or type 2 diabetes, depending on how the variant affects the protein function." (PMID 38932873, 2024). "CYP2C9 encodes sulfonylurea metabolizing cytochrome P450 isoenzyme 2C9, ABCC8 and KCNJ11 genes encode proteins constituting ATP-sensitive K+ channel which is a therapeutic target for sulfonylureas, and TCF7L2 is a gene with the strongest association with type 2 diabetes." (PMID 24324494, 2013). "Of the 132 type 2 diabetes Knowledge Portal effector genes, we identified 18 (14%) as candidate effector genes for at least one phenotype, including ABCC8, KCNJ11, NKX2–2, G6PC2, PAM, HNF4A, SLC30A8, RFX6, PCSK1, and GLIS3." (PMID 37333221, 2023). "Potassium inwardly rectifying channel, subfamily J, member 11 (KCNJ11) gene have a key role in insulin secretion and is of substantial interest as a candidate gene for type 2 diabetes (T2D)." (PMID 25247988, 2014). "Here, we have investigated the role of three type 2 diabetes candidate SNPs well-known in other populations (TCF7L2 rs7903146, KCNJ11 rs5219, PPARγ rs1801282) in more than 1000 Ghanaians." (PMID 24059590, 2013). "In this study, we confirmed the effects of variations in PPARG, KCNJ11, CDKAL1, CDKN2A-CDKN2B, IDE-KIF11-HHEX, IGF2BP2 and SLC30A8 on type 2 diabetes." (PMID 19862325, 2009).
type 2 diabetes (continued). "We did not detect statistically significant interactions between coffee consumption and five SNPs related to type 2 diabetes (CDKAL1 rs7756992, CDKN2A/B rs10811661, KCNJ11 rs5215, KCNQ1 rs163184, and PEPD rs3786897) in the association between coffee and the risk of type 2 diabetes." (PMID 32722593, 2020). "We showed that sulfonylurea failure, commonly seen in type 2 diabetes, is not a feature of KCNJ11 permanent neonatal diabetes." (PMID 29880308, 2018). "In another study, allele-specific expression of several genes in islets (ANPEP, CAMK2B, HMG20A, KCNJ11, NOTCH2, SLC30A8 and WFS1) showed that even subtle changes of gene dosage may have significant consequences for development of type 2 diabetes." (PMID 30497374, 2018). "We have previously examined common genetic variation in several candidate gene loci (i.e., KCNQ1, KCNJ11, CDKAL1, and FTO genes) and confirmed some but not all of their associations with type 2 diabetes in the SDS." (PMID 21062480, 2010). "Second, in KCNJ11 permanent neonatal diabetes, high-dose sulfonylureas facilitate the response to alternative pathway stimuli and do not directly stimulate insulin secretion as in type 2 diabetes." (PMID 29880308, 2018). "Despite the absence of monoclonal antibodies against known type-2 diabetes small molecule targets ABCC8, ABCC9, DPP4, and KCNJ11, these genes demonstrated AB tractability estimates greater than 60%, along with interleukin receptors IL4R and IL17RA." (PMID 37225853, 2023).